STRA6LP (STRA6 like, pseudogene)
Gene: Transcribed unitary pseudogene on chromosome 9 (97,276,569 to 97,295,765, forward strand). Ensembl gene ENSG00000254633.
Diseases named in the same sentence as STRA6LP in open-access papers:
STRA6LP is named in the same sentence as 1 disease in open-access papers, as found by Europe PMC text mining. Sharing a sentence is not in itself a finding about the gene and the disease. The quoted sentences say what the papers report.
cancer (1 paper, 2021). A tumor composed of atypical neoplastic, often pleomorphic cells that invade other tissues. "The lncRNAs XIST, TTN-AS1, STRA6LP, and TSIX had high numbers of mutations in most cancers, which play an important role in the oncogenic mechanism." (PMID 34079798, 2021).